SHOC2 (SHOC2 leucine rich repeat scaffold protein)
Diseases named in the same sentence as SHOC2 in open-access papers (continued):
Sharing a sentence is not in itself a finding about the gene and the disease.
cancer (continued). "Inhibitors of the SHOC2 holophosphatase may have activity as single agent in RAS-driven cancers and widen the therapeutic index of MEKi alone or in combination with other targeted agents against the many cancers with high RAS activity." (PMID 31182717, 2019). "Several reports support this possibility and thus, SHOC2 could also provide a useful target for combination therapies against BRAF-mutant cancers in some contexts." (PMID 31182717, 2019). "Regardless, SHOC2’s contribution to tumorigenic properties in some RAS-mutant human cells lines, as well as to tumor development in a KRAS-driven mouse LUAD model suggests targeting SHOC2 in the clinic may have activity as monotherapy against a subset of RAS-mutant cancers." (PMID 31182717, 2019). "Therefore, our study suggested that Shoc2 was a functional target of Celastrol in cancers." (PMID 30333251, 2018). "Overall, our findings define isoform-specific differences in SHOC2-RAS-PP1C complex formation and support a strategy to prevent both SKP and SMP assemblies to overcome resistance in RAS-driven cancers." (PMID 41519889, 2026). "Yet, cancers driven by oncogenic KRAS, HRAS, or NRAS remain strongly SHOC2-dependent, suggesting that these weaker complexes contribute to tumorigenesis." (PMID 41519889, 2026). "CircRNA profiling by microarray revealed a potential role of circ_IPCEF1 in PTC and showed interactions with four cancer-related genes, “CASR, CDC25B, NFκB1, and SHOC2” through sponging miR-3619-5p." (PMID 36230649, 2022). "Genetic knockout of Shoc2 suppresses the growth of a subset of KRAS-mutant cancer cell lines and inhibits tumour growth in mouse models of KRAS-driven lung cancer, demonstrating that SHOC2 function is critical for RAS–RAF pathway activation." (PMID 35768504, 2022). "Our study uncovers new insights into SHOC2 biology and reveals inhibition of the SHOC2 phosphatase complex, alone and in combination with MEKi’s, as a therapeutic strategy to treat RAS- and EGFR-mutant cancers." (PMID 31182717, 2019). "Numerous cancer cell lines exhibit a strong correlation or dependency on mutant H/K/NRAS and SHOC2." (PMID 35768504, 2022). "It is known that NRAS‐mutant cancer cell lines rely on signalling through CRAF (RAF1) and SHOC2 and we could identify this association as a highly significant association in CEN‐tools." (PMID 33073517, 2020). "BRAF-mutant cancer cells are not sensitized to MEKi in the absence of SHOC2, which is consistent with signalling by oncogenic BRAF being independent of RAF dimerization and therefore of SHOC2 phosphatase function." (PMID 31182717, 2019).
tumor (18 papers, 2012 to 2025). "Our study aligns with this observation, suggesting that SHOC2 plays a vital role in the survival advantage of RAS mutants in multiple tumor types (Skin, Haemato-lymphoid) by working with mutated RAS." (PMID 39455841, 2024). "Treatment with a low dose of the MEKi Trametinib (0.4 mg/kg) that only had a cytostatic response in tumours from control cells, caused marked tumour regressions of SHOC2 KD cells that persisted beyond the treatment window." (PMID 31182717, 2019). "On the other hand, Shoc2 KO significantly reduced the pErk1/2 levels in tumor tissues as well as in adjacent normal tissues." (PMID 39871893, 2024). "Consistently, the H&E staining revealed that the Pten−/−;Shoc2−/− mice had remarkably elevated tumor burden in the livers." (PMID 39871893, 2024). "The complex of PP1 with the leucine-rich repeat protein SHOC2 promotes tumor growth in a subset of KRAS-mutant NSCLC cell lines by dephosphorylating a critical inhibitory site on RAF kinases, resulting in RAF-ERK pathway activation." (PMID 36966223, 2023). "SHOC2 inactivation, using either KO or KI models, significantly decreased overall tumour burden, and significantly, prolonged overall survival in both K and KP animals." (PMID 31182717, 2019). "In summary, our study is the first to confirm that Celastrol exerts anti-tumor functions in human CRC at least partially by inhibiting ERK1/2 phosphorylation via its binding to Shoc2." (PMID 30333251, 2018). "We demonstrated that inhibition of Shoc2 by Celastrol reduced ERK1/2 phosphorylation and that down-regulation of Shoc2 significantly inhibited tumor growth." (PMID 30333251, 2018). "Shoc2 activates ERK1/2 to promote tumor development through regulation of contact inhibition and cell polarization." (PMID 30333251, 2018). "Thus, it appears that SHOC2 acts as an oncogene by activating the RAS/MAPK or a tumor suppressor by inactivating the mTORC1 signals, respectively, to regulate the growth and survival, and liver tumorigenesis." (PMID 39871893, 2024). "Importantly, both SHOC2 and PSMC1 are often up-regulated in human malignancies and have been linked to cellular transformation and tumor metastasis." (PMID 38753575, 2024). "Collectively, it appears that SHOC2 could act as either an oncogene (via activating the MAPK signal) or a tumor suppressor (via inactivating the mTORC1 signal) in the manner dependent of the dominancy of the MAPK vs. mTORC1 signals." (PMID 39871893, 2024). "Moreover, we found that Prkcsh, Tra2a, and Shoc2 are underexpressed at the tumor’s periphery compared to its center and mid-zones." (PMID 36151122, 2022). "In this study we show that genetic inhibition of SHOC2 suppresses tumour development and elongates overall survival in KRAS-driven Lung adenocarcinoma (LUAD) mouse models, as well as inhibiting tumorigenic growth in a subset of KRAS- and EGFR-mutant human cell lines." (PMID 31182717, 2019). "Down-regulation of Shoc2 expression also inhibited tumor cell proliferation and migration." (PMID 30333251, 2018). "Furthermore, down-regulation of Shoc2 expression also significantly inhibited proliferation, colony formation, and migration functions of tumor cells." (PMID 30333251, 2018). "SHOC2 can also promote the expression of LGALS3BP (lectin galactoside-binding soluble 3 binding protein) and so on to control the effect of ERK1/2 pathway on cell movement and adhesion, and the high expression of such proteins in blood and tumor tissues was associated with poor prognosis." (PMID 37166421, 2023). "To assess the co-dependency of tumour cell lines on SHOC2 and RAS, we correlated chronos scores for SHOC2 and either MRAS or HRAS, KRAS or NRAS from all 1,061 tumour cell lines in DepMap." (PMID 35768504, 2022). "SHOC2 inhibitor cooperated with MEK inhibitor or EGFR-TKI impairs cell proliferation and viability in KRAS- or EGFR mutant driven tumor cells." (PMID 34102455, 2021).
tumor (continued). "SHOC2 ablation in both the LSL-KrasG12D, and more aggressive KrasG12DTrp53R172H LUAD mouse model, potently suppresses tumour development and extends lifespan, as has been shown previously for B & CRAF ablation in the LSL-KrasG12D model." (PMID 31182717, 2019). "Surprisingly, the inactivation of Mapk signals triggered by Shoc2 deletion unexpectedly did not translate to reduced tumor burden, suggesting the potential involvement of other pathway genes in driving DEN-initiated liver tumorigenesis." (PMID 39871893, 2024). "As seen with SHOC2, intrapathway dual inhibition (vertical inhibition) at the level of RAF or ERK (MEKi plus RAFi or MEKi plus ERKi) also impairs feedback reactivation, leads to more potent and sustained ERK suppression, promotes tumour regression in preclinical models in RAS-mutant cells." (PMID 31182717, 2019).
infection (1 paper, 2024). The state of being infected such as from the introduction of a foreign agent such as serum, vaccine, antigenic substance or organism. "While only cells expressing SHOC2 sgRNA-A displayed statistically-significant differences in RRV-GFP infection, SHOC2 sgRNA-B-expressing cells trended towards an increased susceptibility to this virus with an ~9-fold higher mean in GFP signal than empty vector controls." (PMID 38753575, 2024). "Interestingly, cells expressing either SHOC2 sgRNA-A or sgRNA-B were significantly more susceptible to infection with ONNV-GFP, SINV-GFP, and VSV-GFP infection." (PMID 38753575, 2024). "We showed that 786–0 cells became sensitive to VSV-M51R infection after either overexpression of IpaH4 or knockdown of IpaH4 substrates, PSMC1 and SHOC2." (PMID 38753575, 2024). "Interestingly, at least 2/3 and 3/3 siRNAs targeting SHOC2 and PSMC1, respectively, sensitized 786–0 cells to VSV-M51R-GFP infection." (PMID 38753575, 2024).
mitochondrial disease (1 paper, 2024). "Patient No. 4 was confirmed to have a Noonan syndrome-like disorder with a pathogenic mutation in the SHOC2 gene, and patient No. 8 was confirmed to have mitochondrial disease (a possibly pathogenic variant m.3761C>A in the MT-ND1 gene causing mitochondrial complex I deficiency)." (PMID 39529965, 2024).
SHOC2 also shares sentences with these, for which no sentence is quoted: cardiofaciocutaneous syndrome (4 papers); glioma (2); adenocarcinoma (1); antiphospholipid syndrome (1); Arrhythmia (1); atrial septal defect (1); bone marrow failure (1); cardiac hypertrophy (1); cardiomyopathy (1); CHARGE syndrome (1); Chylothorax (1); colon cancer (1); colorectal cancer (1); COVID-19 (1); cutaneous T-cell lymphoma (1); Dubin-Johnson syndrome (1); gastroesophageal reflux disease (1); genetic disorder (1); hematologic malignancies (1); hepatocellular carcinoma (1); keratoconus (1); Legius syndrome (1); Li-Fraumeni syndrome (1); lymphangiectasia (1); lymphedema (1); lymphoma (1); malaria (1); metastatic melanoma (1); neurofibromatosis (1); neurofibromatosis type 1 (1).
A further 6 diseases each share a sentence with SHOC2 in 1 paper.